ABCC2 (ATP binding cassette subfamily C member 2)
Diseases named in the same sentence as ABCC2 in open-access papers (continued):
Sharing a sentence is not in itself a finding about the gene and the disease.
cholestasis (22 papers, 2012 to 2026). Impairment of the bile flow caused by obstruction within the liver, or outside the liver in the bile duct system. "ABCC2 gene has been implicated in drug and estrogen-induced cholestasis." (PMID 38992651, 2024). "Interestingly, in DSS/chow mice there was moderate suppression of Abcb11 mRNA at the 14-day time point and suppression of Abcc2 mRNA at the 7-day and 14-day time points, yet, importantly, this reduced transporter expression alone was insufficient to cause cholestasis." (PMID 29643332, 2018). "Based on the current findings, it is only effective for cholestasis caused by the UGT1A1, ABCB11, and ABCC2 gene mutations." (PMID 39981091, 2025). "In another study, the expression of Abcc2 in the liver was controlled by nuclear receptor activation, which is impaired during cholestasis." (PMID 38168520, 2023). "Ursodeoxycholic acid (UDCA), used as a treatment for patients with cholestasis, was also shown to stimulate the targeting of ABCC2 and ABCB11 transporters to the plasma membrane." (PMID 33672718, 2021). "The risk of cholestasis in pregnancy has been associated with genetic variants in ABCB4, ABCB11, ATP8B1, ABCC2, and TJP2 genes." (PMID 34557220, 2021). "Mutations in the ABCC2 gene cause abnormalities in the function of MRP2, resulting in cholestasis and black liver as a result of the failure to release bilirubin and bile into the bile ducts." (PMID 32758197, 2020). "Changes in the expression of genes indicative of cholestasis represented changes in the transporters ABCC2 and UGT2B4, which are up-regulated by the farnesoid X receptor and are involved in the glucuronidation of the bile acid hyodeoxycholic acid." (PMID 30572671, 2018). "Concomitant with biochemical cholestasis, mRNA expression of Abcb11 and Abcc2 was significantly suppressed in DSS/PN14d mice." (PMID 29643332, 2018). "Variations in ABCC2 gene were found to be associated with cholestasis and nonalcoholic fatty liver disease." (PMID 39567526, 2024). "For example, TNF-α can inhibit the transcription of the tubule bile acid transporter Abcb11, bilirubin outlet Abcc2, and sterol transporter Abcg5/8 in intestinal inflammation, cholestasis, or the activation of hepatic macrophages, and thus affect the expression of transporters." (PMID 35163972, 2022). "IL-1β increases hepatocyte NF-κB signaling, which interferes with farnesoid X receptor and liver X receptor bonding to respective promoters of canalicular bile and sterol transporter genes (Abcc2, Abcb11, and Abcg5/8), resulting in transcriptional suppression and subsequent cholestasis." (PMID 29643332, 2018). "Interestingly, despite carrying two ABCC2 gene mutations, the mother has no history of cholestasis." (PMID 39100650, 2024). "Here, we reviewed the leading molecular pathways between the DIC and ABCB1, ABCC2, ABCB11, and ABCB4 genes, the links with the other clinical forms of familial intrahepatic cholestasis, and, finally, the main cholestasis-inducing drugs." (PMID 36982896, 2023). "The key role of canalicular ABC transporters in bile secretion is highlighted by their implication in a wide range of diseases such as cholestasis (ABCB4, ABCB11), sitosterolemia (ABCG5/G8), Dubin–Johnson syndrome (ABCC2) and cancer (ABCB1)." (PMID 33672718, 2021). "In a model of estradiol-induced cholestasis, authors showed that following treatment with estradiol-17β-d-glucuronide (E217G), ABCB11 and ABCC2 are relocalized from canalicular membranes to intracytoplasmic compartments." (PMID 33672718, 2021). "Mechanistically, IL-1β appears to mediate cholestasis in PNAC through hepatocellular NF-κB signaling, which interferes with the ability of FXR to bind to and transactivate Abcb11 and Abcc2 promoters, thus reducing canalicular bile and bilirubin transport." (PMID 29643332, 2018).
cholestasis (continued). "Elevated serum bile acids and bilirubin in the face of transcriptional suppression of Abcb11 and Abcc2 therefore strongly implicate insufficient expression of BSEP and MRP2 in the pathogenesis of cholestasis in this model." (PMID 29643332, 2018). "Hepatic mRNA expression of Abcb11 and Abcc2 was suppressed in DSS/PN mice at 3 days, preceding evidence of cholestasis and hepatocyte injury, and were progressively suppressed by 14 days." (PMID 29643332, 2018). "Levels of the bile salt export pump (BSEP/Abcb11) were not decreased in combined steatosis and cholestasis compared to cholestasis, while levels of multidrug resistance-associated protein 2 (MRP2/Abcc2) were (p < 0.05)." (PMID 27535001, 2016).
epilepsy (19 papers, 2013 to 2025). A brain disorder characterized by episodes of abnormally increased neuronal discharge resulting in transient episodes of sensory or motor neurological dysfunction, or psychic dysfunction. "This study showed that children with the T-allele of ATP-binding cassette subfamily C member 2 polymorphism (ABCC2*rs717620) had a higher risk of epilepsy when compared to healthy controls." (PMID 41009999, 2025). "It has also been observed that in patients with epilepsy, ABCC2 rs2273697 and rs3740066 polymorphisms increase blood carbamazepine concentrations." (PMID 36278153, 2022). "Further, in the Asia Pacific epilepsy cohort, ABCC2 rs2273697 and rs3740066 polymorphisms were associated with antiepileptic drug resistance." (PMID 36278153, 2022). "The association between ABCC2 polymorphisms and anti-epileptic drug-resistant epilepsy is discordant." (PMID 33804537, 2021). "Association of ABCC2 rs2273697 and rs3740066 polymorphisms and drug-resistant epilepsy has been reported in Asia Pacific epilepsy cohorts." (PMID 32357528, 2020). "The SCN1A IVS5-91G>A AA and ABCC2 c.1249G>A GA genotypes have been shown to be associated with carbamazepine/oxcarbamazepine-resistant epilepsy in the Chinese Han population." (PMID 32357528, 2020). "The P-gp encoded by the ABCB1 and ABCC2 genes are expressed in drug resistant patients with epilepsy." (PMID 23717663, 2013). "SCN1A rs3812718 and ABCC2 rs2273697 are associated with CBZ/OXC-resistant epilepsy." (PMID 39228521, 2024). "The overexpression of ABCC2 primarily in endothelial cells of the hematoencephalic barrier, liver, intestine, kidney, placenta, and lungs has been reported to be a risk factor for the resistance to drugs used in epilepsy, cancer, and hepatitis." (PMID 30018187, 2018). "Furthermore, only two meta-analyses investigated its role in drug-resistant epilepsy and found that ABCC2 G1249A polymorphism was significantly associated with the decreased risk of AED resistance." (PMID 28202008, 2017). "The results of this study indicate that the ABCC2 1249G>A (rs2273697) and ABCC2 −24C>T (rs717620) polymorphisms affect the plasma concentrations and treatment efficacy of LCM in pediatric patients with epilepsy, leading to drug resistance." (PMID 36253887, 2023). "In clinical practice, ABCC2 polymorphisms should be identified before LCM treatment, and then, the dosage should be adjusted for pediatric patients with epilepsy accordingly." (PMID 36253887, 2023). "This study is the first to evaluate the effect of ABCC2 polymorphisms on the plasma concentrations and efficacy of LCM in Uygur pediatric patients with epilepsy." (PMID 36253887, 2023). "Research suggests that ABCC2 rs717620 and rs3740066 are risk factors that predict a response to AED in patients with epilepsy." (PMID 34769124, 2021). "The current study in patients receiving cisplatin chemotherapy and published data from patients with epilepsy and HIV-1 support the influence of polymorphisms in ABCC2 on biomarker changes and outcomes such as efficacy and toxicity." (PMID 28640195, 2017). "There are ample evidences where overexpression of ABCC2 was observed in epilepsy patients, but the specific contributions of AEDs in the transporter overexpression are still not clear." (PMID 28961159, 2017). "Although the Pgp efflux transport protein is overexpressed in resected tissue of patients with epilepsy, the presence of polymorphisms in MDR1/ABCB1 and MRP2/ABCC2 in patients with antiepileptic-drugs resistant epilepsy (ADR) is controversial." (PMID 25346718, 2014). "Therefore, this study was conducted to evaluate the association of the 1249G>A and −24C>T genotypes of ABCC2 as well as their haplotypic and diplotypic combinations with the plasma concentration and efficacy of LCM in Uygur pediatric patients with epilepsy." (PMID 36253887, 2023).
epilepsy (continued). "We aimed to evaluate the effect of the ABCC2 1249G>A (rs2273697) and −24C>T (rs717620) polymorphisms on lacosamide (LCM) plasma concentrations and the efficacy of LCM in Uygur pediatric patients with epilepsy." (PMID 36253887, 2023). "The ABCC2 1249G>A (rs2273697) and ABCC2 −24C>T (rs717620) polymorphisms can affect plasma LCM concentrations and treatment efficacy among a population of Uygur pediatric patients with epilepsy, causing these patients to become resistant to LCM." (PMID 36253887, 2023). "However, the expression level of ABCC2 is relatively low in normal brain tissue, whereas the expression level of ABCC2 in the brain tissue of patients with epilepsy is relatively increased." (PMID 35290166, 2022). "Studies have shown that the up-regulation of ABCC2 expression in brain tissue in patients with epilepsy may be related to the efficacy and distribution of the drug in the body." (PMID 35290166, 2022). "The screening of SNPs in ACBC1 and ABCC2 indicates that the Mexican patients with epilepsy in this study display frequently reported ABCC1 polymorphisms; however, in the study subjects with a higher risk factor for drug resistance, new nucleotide changes were found in the ABCC2 gene." (PMID 25346718, 2014). "Indeed, nonsynonymous polymorphism c.1249G>A was associated with reduced CBZ transport but not with drug response in epilepsy patients, while the A-allele of ABCC2 single nucleotide polymorphism c.1249G>A is related to neurological ADRs." (PMID 33804537, 2021). "Allelic and genotype frequencies of the transporters MDR1, ABCG2, ABCC2, and SLC22A1 in Chinese patients with epilepsy." (PMID 31404235, 2019). "No reports are available on the relationship between ABCC2 polymorphism with the plasma concentrations and efficacy of LCM in pediatric patients with epilepsy." (PMID 36253887, 2023). "While most of genes are known to be related to ASD, ID or epilepsy, ABCC2, CCDC50 and SLC26A4 were not reported to be related to neurodevelopmental disorder according to OMIM." (PMID 32477112, 2020). "Among the top SNPs present in the best prediction model, the fourth most important variable for the model (rs2756104) is located in ABCC2, prompting us to analyse mRNA expression in the hippocampal tissue of patients with refractory MTLE who underwent epilepsy surgery." (PMID 28052106, 2017).
hepatocellular carcinoma (17 papers, 2015 to 2025). A malignant tumor that arises from hepatocytes. "An in-vitro study on hepatocellular carcinoma cell lines showed that ABCC2 has a critical role in hypoxia-induced resistance by curcumin." (PMID 35405942, 2022). "Previous studies showed that UPF1 inhibits the hepatocellular carcinoma progression by targeting MRP2/ABCC2 or long non-coding RNA UCA1." (PMID 34922601, 2021). "ABCC2 is a well-known transporter in the context of CDDP resistance, and ABCC2 level is considered as predicting clinical effects in esophageal squamous cell carcinoma and hepatocellular carcinoma." (PMID 29765522, 2018). "Targeting ABCC2 by antisense RNA reduces the doxorubicin IC50 value by 12-fold in hepatocellular carcinoma cells, whereas overexpression of ABCC2 in HEK293 cells enhances doxorubicin resistance around 8-fold." (PMID 27029062, 2016). "In human hepatoma cells, PPARα also regulates hepatic genes, including multidrug resistance protein 1 (MDR1), multidrug resistance-associated protein 2 (MRP2/ABCC2), MRP3, and MRP4, which encode ABC transporters known to play a vital role in effluxing bile acids and therapeutic drugs." (PMID 37474902, 2023). "However, ABCC2 was shown to be down-regulated by hepatitis B virus core protein in the combined proteomics and metabolomics approach in hepatocellular carcinoma cells." (PMID 33865438, 2021). "UPF1 can prevent cancer stem cell (CSC)-like properties and inhibit the epithelial-mesenchymal transition (EMT) process via decreasing ABCC2 expression in hepatocellular carcinoma (HCC)." (PMID 35871061, 2022). "Therefore, the expression of ABCC2 mRNA is upregulated during human hepatic carcinoma development." (PMID 26665149, 2015). "Our group has shown that GH elevates the specific ABC transporters, such as ABCC1, ABCC2, ABCB1, and ABCG2 in melanoma, hepatocellular carcinoma, and pancreatic cancer." (PMID 39123364, 2024). "In addition, ABCC2 has been detected in various solid tumors, such as hepatocellular carcinoma (HCC), head and neck squamous cell carcinoma (HNSCC), esophageal squamous cell carcinoma (ESCC), papillary renal cell carcinoma, and colon cancer." (PMID 38612927, 2024). "Furthermore, in vitro experiments in primary mouse hepatocytes and human hepatoma cell lines HuH7 and HepG2 together with in vivo experiments demonstrated that IL-1β exposure was sufficient to suppress transcription of Nr1h4, Abcb11, Abcc2, and Abcg5/8, findings that characterize the PNAC liver." (PMID 29643332, 2018). "In hepatocellular carcinoma, MDR is mediated by ABCB1, ABCB5, ABCC1, ABCC2, and ABCG2." (PMID 36557005, 2022).
ovarian carcinoma (17 papers, 2010 to 2025). A malignant neoplasm originating from the surface ovarian epithelium. "In contrast, ABCC2 rs12762549 is associated with decreased risk of grade 3-4 anemia in additive model (OR = 0.51; 95% CI: 0.33–0.81; p = 0.004) among 290 ovarian cancer patients upon treatment with paclitaxel and carboplatin." (PMID 39234108, 2024). "High ABCA1 and ABCC2 mRNA were significantly associated with reduced PPS in all ovarian cancer subtypes and HGSOC." (PMID 35582032, 2021). "After the long‐term use of platinum drugs in patients with ovarian cancer, lung cancer and colon cancer, the ABCC2 gene is often upregulated in some parts of these patients and upregulation of the ABCC2 gene usually causes patients to develop resistance to platinum drugs." (PMID 32815556, 2021). "A recent study showed that ISG15 suppresses the translation of multidrug resistance-associated protein 2 (MRP2/ABCC2) via ISGylation of hnRNPA2B1 and enhances drug sensitivity in cisplatin-resistant ovarian cancer cells." (PMID 37391814, 2023). "Several studies have shown that ABCC2 SNPs mediate the efflux of irinotecan, cisplatin, and methotrexate from intracellular to extracellular spaces in colorectal cancer, ovarian cancer, and acute lymphoblastic leukemia." (PMID 36278153, 2022). "ISG15 overexpression downregulates ATP binding cassette subfamily C member 2 (ABCC2) and facilitates sensitivity to cisplatin in cisplatin-resistant ovarian cancer cells." (PMID 36319753, 2022). "In ovarian cancer, upregulation of miR‐490‐3p enhanced the sensitivity of ovarian cancer cells to DDP by downregulating ABCC2 expression." (PMID 32815556, 2021). "It has been shown that suppression of ABCC2 by siRNA-mediated knockdown was able to restore sensitivity of cisplatin-resistant ovarian cancer cells to platinum and taxane treatment." (PMID 29464053, 2018). "The co-localization of CD44 with ABCB1 and ABCC2 in ovarian cancer tissues suggests a functional link between CD44 expression and chemoresistance." (PMID 24124770, 2013). "Overexpression of ABCC1 and ABCC2 in human ovarian cancer cells conferred marked resistance to chemotherapeutics, such as methotrexate." (PMID 24124770, 2013). "Carboplatin significantly increased expression of HAS2, HAS3 and ABCC2 and HA secretion in ovarian cancer cell conditioned media." (PMID 24124770, 2013). "Previous studies confirmed that ABCC2 was localized in the nuclear membrane of CDDP-resistant cells, and nuclear membranous localization of ABCC2 correlated with resistance against CDDP in ovarian carcinoma cells." (PMID 20628484, 2010). "High ABCC2 and ABCG2 expressions were associated with increased PFS in all ovarian cancer subtypes." (PMID 35582032, 2021). "A previous study examining crocin derived from saffron (Crocus sativus L.)plant in cisplatin-resistant ovarian cancer cells (A2780/RCIS) demonstrated a strong inhibitory effect on the mRNA expression of ABCC1 and ABCC2." (PMID 41303640, 2025). "In this regard, ISG15 has been reported to inhibit ABCC2 expression and re-sensitize CDDP-R ovarian cancer cells." (PMID 37174688, 2023). "This study investigated the relationship of the five ABC transporters ABCA1, ABCB1, ABCB3 (also known as TAP2), ABCC2 and ABCG2 with ovarian cancer chemoresistance and outcome." (PMID 35582032, 2021). "Our data supports a role for ABCB3, ABCC1, ABCC2, and ABCC3 in ovarian cancer chemoresistance, which is in agreement with previous studies." (PMID 24124770, 2013). "Other ABC transporters, including ABCB3 (TAP2), ABCC1 (MRP1), ABCC2 (MRP2, cMOAT), and ABCC3 (MRP3), have been shown to be involved in ovarian cancer chemoresistance." (PMID 24124770, 2013). "Our results show that HA induces chemoresistance against CBP, and increases the expression of the ABC transporters, ABCB3, ABCC1, ABCC2, and ABCC3 in ovarian cancer cell lines expressing the HA receptor, CD44." (PMID 24124770, 2013).
ovarian carcinoma (continued). "The trials did not select patients by ABC transporter expression, and clinical trials targeted ABCB1 and ABCG2 (with only a few targeting ABCC2), but other ABC transporters also likely to play important roles in ovarian cancer progression and chemotherapy resistance." (PMID 35582032, 2021). "Indeed, previous studies showed that suppression of IGF-1R decreases ABCC2 expression and promoted drug sensitivity in human colon cancer cells, and that IGF-1 increased the expression of ABCC1, ABCC2, and ABCC3 in both leukemia cells and ovarian cancer cells." (PMID 33291663, 2020). "Furthermore HA treatment significantly increased the expression of ABC drug transporters (ABCB3, ABCC1, ABCC2, and ABCC3), but only in ovarian cancer cells expressing CD44." (PMID 24124770, 2013). "We investigated whether CBP increases HA production and the expression of ABCC2, an ABC transporter shown to confer ovarian cancer cell resistance to platinum based chemotherapy agents including CBP." (PMID 24124770, 2013). "Additionally, carboplatin treatment increased hyaluronan expression in ovarian cancer cells, leading to chemoresistance by the upregulation of the membrane ATP-binding cassette transporter proteins (ABCB3, ABCC1, ABCC2, and ABCC3) in CD44-expressing ovarian cells." (PMID 36984544, 2023).